MCL1 (MCL1 apoptosis regulator, BCL2 family member)
Diseases named in the same sentence as MCL1 in open-access papers (continued):
Sharing a sentence is not in itself a finding about the gene and the disease.
cancer (1,212 papers, 1999 to 2026). A tumor composed of atypical neoplastic, often pleomorphic cells that invade other tissues. "β-TrCP is a well-characterized F-box protein that targets several cell cycle- and apoptosis-related substrates, including β-catenin, IκBα, and MCL1, and is frequently implicated in cancer signaling." (PMID 41154579, 2025). "Overexpression of anti-apoptotic proteins (e.g., Bcl-2, Bcl-xL, Mcl-1) is a common hallmark across various cancers, often exhibiting distinct patterns of expression in different cancer types such as breast, gastric, lung, and prostate cancers." (PMID 40841912, 2025). "This compound, wogonin, inhibits the antiapoptotic proteins like MCL‐1 and makes the cancer cell susceptible to apoptosis." (PMID 41164269, 2025). "Apoptosis evasion is a cancer hallmark, mediated by aberrant expression and survival dependence on anti-apoptotic members of the Bcl-2 family (Bcl-2, Bcl-xL, and Mcl-1), which function to sequester pro-apoptotic proteins (Bak and Bax)." (PMID 40707672, 2025). "To further confirm that the loss of Gln-K604 promotes c-Myc and Mcl-1 overexpression and apoptosis resistance, we evaluated the effects of glutaminol, a structural analog of glutamine, in cancer cells." (PMID 40338031, 2025). "The anti-apoptotic BCL2 family member MCL1 is overexpressed in many cancers and has been linked to chemoresistance." (PMID 40909578, 2025). "Overexpression of MCL1 has been associated with resistance to T cell-mediated cytotoxicity in various cancer cell types and mouse xenografts, through regulation of the mitochondrial apoptotic pathway and activation of the NF-κB pathway." (PMID 38538696, 2024). "The enhanced stabilization of MCL-1 makes these cancer cells more susceptible to MCL-1 targeting, a phenomenon previously observed in other models." (PMID 38898061, 2024). "Mcl-1 is frequently overexpressed in various cancer types, and its overexpression has been implicated in promoting cancer cell survival, growth, chemoresistance, and metastasis." (PMID 38474118, 2024). "In recent years, MCL1 upregulation has been implicated in therapeutic resistance in various types of cancer and other diseases." (PMID 38485916, 2024). "In NSCLC cells with EGFR activating mutations, blockade of EGFR signaling accelerates MCL-1 degradation and triggers cancer cell apoptosis." (PMID 39543744, 2024). "In this context, Noxa antagonizes the function of Mcl-1, and therefore high levels of Noxa render cancer cells susceptible to BH3 mimetics, such as ABT263 and ABT199, also known as navitoclax and venetoclax, respectively." (PMID 38483541, 2024). "KS18 is positioned as a potentially safer and similarly effective Mcl-1 inhibitor, necessitating additional exploration in MM and associated cancers." (PMID 39411073, 2024). "Myeloid cell leukemia-1 (MCL-1), which belongs to the anti-apoptotic B cell lymphoma-2 family protein, is overexpressed in various cancers and is associated with cell immortality, malignant transformation, chemoresistance, and poor prognosis in humans." (PMID 39012900, 2024). "Survival analyses of publicly available data further supported the clinical relevance of this approach, by confirming that higher MCL1 gene expression is associated with lower overall survival for cancer patients treated with anti-PD-1." (PMID 38459020, 2024). "How can one overcome the dose-limiting toxicity associated with MCL1 inhibitors, and how can one overcome the intrinsic resistance observed in some cancer cells?" (PMID 39802137, 2024). "Activation of STAT3 and upregulation of MCL1 have been previously associated with cancer cell survival and resistance to cell death." (PMID 38485916, 2024). "In order to understand the antilymphoma properties of the acyclic terpenoids Gg, PT and FA and how they affect U-937 cells, we decided to study three potential targets associated with cancer, including Bcl-2, Mcl-1 and VEGFR-2." (PMID 38731446, 2024).
cancer (continued). "Aberrant expression of MCL1 has been linked to poor prognosis and resistance to chemotherapeutic and targeted agents in various cancers." (PMID 38371625, 2024). "Overexpression of MCL1 in different cancers is associated with disease severity and poor prognosis, underscoring the pro-survival role of this oncoprotein." (PMID 39386614, 2024). "Loss of function of the tumor suppressor F-box WD-40 domain containing 7 (FBW7) mutations leads to the accumulation of its substrate MCL-1 which is associated with Taxol resistance in human cancers." (PMID 36672454, 2023). "They resensitize cancer cells through the downregulation of MCL-1 expression in the FLT3 mutated cells, resulting in the stronger efficacy of BCL-2 inhibitors." (PMID 37958832, 2023). "Mcl-1 overexpression is implicated in cancer drug-resistance, as blocking apoptosis allows cells to survive cytotoxic chemotherapeutic challenge." (PMID 37663116, 2023). "Loss of function FBW7 mutations leads to MCL-1 protein accumulation which culminates in chemotherapy resistance of cancer cells." (PMID 36672454, 2023). "Overexpression of the anti-apoptotic protein MCL-1 is associated with a plethora of human cancers, and it reduces the sensitivity of cancer cells to approved chemotherapies." (PMID 38024975, 2023). "Particularly, the upregulation of anti-apoptotic proteins, such as Bcl-2, Bcl-xL, Mcl-1 and surviving, is associated with cancer progression, tumorigenesis and treatment resistance." (PMID 37686541, 2023). "While Bcl-2 family members are often involved in translocations, Mcl-1 mutations in cancer are rare, yet it is one of the highest amplified genes found in human cancer cells." (PMID 37686541, 2023). "A number of antiapoptotic factors contribute to apoptosis deficiency in cancer cells, with a special focus on antiapoptotic Bcl-2 proteins, such as Bcl-2, Bcl-xL, Bcl-w, and Mcl-1." (PMID 36902392, 2023). "MCL1 plays an important role in cancer development and has been associated with drug resistance in a variety of cancers." (PMID 37900961, 2023). "Myeloid cell leukemia 1 (MCL-1) is frequently overexpressed and amplified in human cancers, which is associated with a poor prognosis." (PMID 36553449, 2022). "Several studies have further revealed that Mcl-1 amplification is a crucial factor in chemoresistance, which is associated with poor prognosis in patients with cancer." (PMID 35625692, 2022). "Because recurrent Mcl-1 mutations are rare, cancer cells must find other ways to overcome this susceptibility in order to maintain Mcl-1 expression." (PMID 35745769, 2022). "Apart from USP9X, USP13 and USP7 have been implicated in deubiquitination and thereby stabilization of Mcl-1 in various cancer settings." (PMID 36045907, 2022). "Mcl-1 overexpression has been linked to the acquired cisplatin resistance in cancer cells belonging to various lineages and that its targeted downregulation or pharmacological inhibition sensitized these cells to cisplatin." (PMID 36045907, 2022). "We herein present a novel and unexpected role for MCL-1: its contribution to the myofibroblastic phenotype and pro-invasive capacity of cancer-associated fibroblasts." (PMID 36104324, 2022). "Evidently, the therapy resistance contributed by Mcl-1 has been associated with cancer stem cell-like features in a variety of tumors." (PMID 36045907, 2022). "Upregulated expression of MCL-1 following the loss of FBXW7 has been described in many cancer types and shown to correlate with increased resistance of tumor cells to various therapies." (PMID 35346215, 2022). "MCL1 is an attractive therapeutic target, being frequently overexpressed and associated with poor prognosis in cancer, with several MCL1 inhibitors currently in phase I/II clinical studies." (PMID 36214609, 2022).
cancer (continued). "Buxifoliadine E, an acridone alkaloid from Atalantia monophyla that acts as Erk inhibitor, inhibited Erk enzyme activity, which causes inhibition of Mcl-1 expression, increasing Bax, which induced caspase-3 activation and apoptosis of cancer cell." (PMID 35744993, 2022). "MCL-1 causes increased metabolic flux through mFAO in response to nutrient deprivation, and this supports the assumption of enhanced mFAO in cancer cells with higher expression of MCL-1." (PMID 35178152, 2022). "Previous studies showed that the anti-apoptotic Bcl-2 family protein Mcl-1 is associated with cancer progression and metastasis." (PMID 36039387, 2022). "The increased expression of MCL-1 has been observed in human cancers and has been associated with the induction of resistance to chemo-radiotherapy and targeting therapy." (PMID 33922992, 2021). "Due to this feature, inhibition of Mcl-1 expression and/or neutralisation of its anti-apoptotic function will rapidly make Mcl-1-dependent cells more susceptible to apoptosis and provide an opportunity to combat different types of cancers." (PMID 34344865, 2021). "Stabilized MCL1 is associated with paclitaxel resistance, reduced progression-free survival, and decreased overall survival in various cancers." (PMID 34638252, 2021). "In sum, the enhancement of apoptosis induction and the suppression of the expression of VEGF-A and MCL-1 were associated with the anti-cancer efficacy of magnolol combined with regorafenib in HCC." (PMID 33922992, 2021). "MCL-1 plays important roles in cancer development, and is associated with drug resistance of a variety of cancers." (PMID 33883020, 2021). "In many cancers, overexpression of MCL1 is frequently observed, and associated with resistance to cytotoxic therapies." (PMID 33445467, 2021). "Recently, a clinical study indicated that constitutive STAT3 activation caused the expression of Mcl-1 and Bcl-xL, resulted in cancer cell progression and survival." (PMID 34488773, 2021). "The underlying mechanism for liver tumorigenesis caused by Mcl-1 deficiency is likely due to excessive apoptosis in hepatocytes, which is known to induce overwhelming inflammation responses and promote cancer development in the liver." (PMID 34336857, 2021). "The physiological significance of MARCH5 as a tumor suppressor gene through regulation of MCL1 is further supported by its genomic loss in a subset of cancers." (PMID 32484436, 2020). "Many downstream genes of STAT3 have been identified in human cancers, including genes associated with cell cycle (cyclin D1 and cMyc), apoptosis (Bcl2-xL and Mcl-1) and metastasis (MMP1 and MMP2)." (PMID 32161621, 2020). "Regulation of MCL1 stability during mitosis is therefore an important aspect of mitotic arrest and defines the susceptibility of cancer cells to MTA treatment." (PMID 32015503, 2020). "Overexpression or amplification of Mcl-1 is frequently observed in human cancers and associated with poor prognosis." (PMID 32276600, 2020). "We first disclosed that MCL1 amplification of a human cancer was associated with lower quantitative values of the PD-L1 CPS and pretreatment hemoglobulin." (PMID 32527042, 2020). "Hits for the PF-NSC-like program included Wnt-signaling regulator LGR5 and the anti-apoptotic gene MCL1, as well as the cancer stemness-associated genes as potential druggable vulnerabilities." (PMID 32663469, 2020). "Altered expression of the pro-survival BCL-2 family proteins (BCL-2, BLC-XL, and MCL1) is a hallmark feature of human cancers, resulting in the activation of complex cellular strategies to evade apoptosis." (PMID 31226848, 2019). "Aberrant increases in levels of anti-apoptotic proteins in the BCL-2 family, such as amplification of MCL1, have been widely implicated in the transformation of cancer cells and the development of resistance to current therapies." (PMID 31294695, 2019).
cancer (continued). "Predicted miR-101-3p targets that were also downregulated by in our microarray were enriched for genes associated with Wnt and cancer pathways, including MCL-1, a member of the BCL-2 family, involved in apoptosis." (PMID 31864341, 2019). "Inactivating this protein complex caused cancer cells to become more sensitive to the MCL1 inhibitor." (PMID 31294695, 2019). "The combination of MCL1 inhibitors with the BCL-2 specific inhibitor venetoclax should be effective against LKB1-mutated cancers and should induce a pronounced sensitization to standard chemotherapy." (PMID 31781355, 2019). "We demonstrated that KPT-330 decreased Mcl-1 protein synthesis through mitigating rRNA processing and global protein synthesis, making cancer cells more susceptible to Bcl-xL inhibitors like A-1331852." (PMID 31113936, 2019). "Taken together, our findings suggest that the anti-cancer effect of fisetin on HNCCs is associated with SESN2/mTOR/Mcl-1 signaling axis." (PMID 30936621, 2019). "This compound potently inhibits the association of Mcl-1 with Bak and is able to kill Mcl-1 overexpressing cancer cells, reverting Mcl-1-mediated resistance to Bcl-2/Bcl-xL/Bcl-w-selective antagonist ABT-737." (PMID 30563080, 2018). "Mcl-1-mediated apoptotic resistance is suggested to be the key cause of cancer cells refractory to ABT-737." (PMID 29543705, 2018). "MCL-1 has been associated with resistance to cancer therapy for some time, and interest has intensified in the development of drugs that specifically target MCL-1." (PMID 29769323, 2018). "Instead, FL118 inhibits the expression of multiple cancer-associated antiapoptotic proteins (survivin, Mcl-1, XIAP, cIAP2) in colon, prostate and ovarian cancer cells." (PMID 30285798, 2018). "Second, we found that atuveciclib treatment decreased protein levels of MYC and MCL1, two major pro-tumorigenic factors regulated by RNA Pol II that are often associated with poor clinical outcomes in many cancer types including TNBC." (PMID 30647871, 2018). "Myeloid cell leukemia-1 (MCL1) gene expression is associated with metastases of various cancers, and tetrac-containing NDAT downregulates this gene." (PMID 30135398, 2018). "Increased expression of MCL-1 has been implicated in resistance to TRAIL induced apoptosis in several cancer types." (PMID 30305055, 2018). "Mcl-1 is a key member of the Bcl-2 anti-apoptotic family, is commonly overexpressed in a number of cancers, and is a major cause of resistance to radio- and chemotherapies." (PMID 29649138, 2018). "Disruption of pathways regulating MCL-1 protein stability also occurs in cancer (e.g. loss or mutation of FBW7 inhibits MCL-1 degradation and is associated with tumorigenesis and resistance to chemotherapy)." (PMID 29769323, 2018). "Gene knockout studies have demonstrated that Mcl-1 is required for embryonic and immune cell development, while its over-expression is implicated in cancer and resistance to cancer treatments." (PMID 28369057, 2017). "Mcl-1 overexpression is one of the most common genetic abnormities in a variety of human cancers, and can be the cause of resistance to several chemotherapeutic agents." (PMID 29254209, 2017). "For example, Bcl-2 and Mcl-1 are highly expressed in cancers, promote cancer cell survival and are associated with poor therapeutic outcomes." (PMID 29156771, 2017). "MCL1 copy number variations have been reported to be associated with cancer prognosis in several cancers." (PMID 29152113, 2017). "Of interest is the observation that several compounds in use or development for cancer treatment also cause MCL-1 inhibition (e.g., CDK inhibitors, MEK inhibitors and PI3K/mTOR inhibitors." (PMID 27056887, 2016). "Treatment of colorectal cancer cells and mesothelioma cells with HSP90 inhibitors resulted in rapid degradation of MCL-1 protein specifically in the cancer cells, causing a sensitisation to TRAIL and ABT-737, respectively." (PMID 27140313, 2016).
cancer (continued). "Overexpression of Mcl-1 is implicated in resistance of several cancers to chemotherapeutic treatment, therefore identifying a safe way to decrease its expression in tumor cells represents a central goal." (PMID 27689327, 2016). "In this study, we investigated using a CHK1 inhibitor as a DNA damaging agent to decrease Mcl-1 protein levels and enhance ABT-199 sensitivity in AML cells, based on a previous report that DNA damage can cause decreased expression of Mcl-1 in cancer cells." (PMID 27166183, 2016). "Overexpression of Mcl-1 has been observed in several human cancers and is implicated in resistance to anti-cancer therapeutics." (PMID 27689327, 2016). "MCL1, an anti-apoptotic protein highly expressed in various cancer cells, has been associated with progression in a number of malignant tumors." (PMID 26918455, 2016). "Overexpression of Mcl-1 is associated with resistance to ABT-737, and inhibition of Mcl-1 has proven to sensitize cancer cells to ABT-737." (PMID 27461218, 2016). "In this study, we elucidate a probable underlying anti-cancer mechanism of chidamide involving the degradation of Mcl-1." (PMID 27875574, 2016). "One oncogenic function of USP9X derives from its interaction with the anti-apoptopic protein MCL1, which is highly expressed in cancers and associated with resistance to chemotherapy." (PMID 25672900, 2015). "Previous data from others and our own group indicated that Usp9X plays a role in the regulation of Mcl-1 and consequently determines susceptibility of cancer cells to the sensitivity of BH3-mimetics." (PMID 26474387, 2015). "Mcl-1 is highly expressed in a variety of human cancers, and it is closely associated with chemo-resistance." (PMID 25890498, 2015). "Like in most cancers, elevated expression of anti-apoptotic Bcl-2 proteins such as Mcl-1, Bcl-2 and Bcl-Xl causes resistance to spontaneous or drug-induced apoptosis in MM." (PMID 25008202, 2014). "Intrinsic resistance to the mitochondrial apoptosis pathway caused by high expression of anti-apoptotic Bcl-2 family members, such as Bcl-2, Bcl-xL and Mcl-1, is a common feature of cancer cells and associated with chemoresistance." (PMID 24948009, 2014). "Very recently, it has been demonstrated that cancer cells in hypoxic conditions are resensitized to ABT-737 by a loss of Mcl-1." (PMID 25192188, 2014). "Mcl-1 is an anti-apoptotic protein that is highly expressed in malignant tumors and has been implicated in resistance to chemotherapy." (PMID 24348795, 2014). "Growing evidence suggests that MCL1 expression levels are associated with worse clinical outcomes in various cancer types." (PMID 25386925, 2014). "Various studies have shown the higher expression of Mcl-1 in several cancers including NSCLCs and associated with resistance to the available treatments." (PMID 23418490, 2013). "Apoptosis, which is a prominent hallmark of cancer, is regulated by myeloid cell leukemia-1 (Mcl-1), an anti-apoptotic member of the BCL-2 family proteins, and the cellular inhibitor of apoptosis protein-1 (cIAP-1)." (PMID 24223741, 2013). "Enhanced Mcl-1 expression has been observed in multiple human cancers, often in association with poor prognosis, disease recurrence, or drug resistance." (PMID 24147107, 2013). "In our current analyses, USP9X expression was found to be strongly associated with Mcl-1 expression in the human cancer tissue samples we tested." (PMID 23171055, 2012). "For example, MCL1 encoded at the 1q21.2 locus frequently exhibits copy number gain in cancer, followed by BCLX (BCLL2)." (PMID 22738201, 2012). "Based on our in vitro observations, we expected that FL118 should effectively inhibit tumor growth in vivo, since FL118 inhibited multiple cancer survival-associated genes (survivin, Mcl-1, XIAP and cIAP2)." (PMID 23029106, 2012). "Maintenance of elevated Mcl-1 expression is associated with drug resistance and poor prognosis in a variety of cancers." (PMID 23056582, 2012).